INS (insulin)
Diseases named in the same sentence as INS in open-access papers (continued):
Sharing a sentence is not in itself a finding about the gene and the disease.
Insulin resistance (continued). "HFD obese mice also exhibited an impairment of glucose metabolism, as showed by the high plasma glucose and insulin levels and the increased Homeostatic Model Assessment for Insulin Resistance (HOMA-IR) index in comparation with STD mice." (PMID 40243721, 2025). "To validate insulin resistance, we measured Akt phosphorylation (p-Akt) following insulin stimulation." (PMID 40956683, 2025). "The lowest activities of β-cells and insulin in the untreated MetS group confirm the rise in insulin resistance." (PMID 40584440, 2025). "In insulin resistance, the average amount of insulin produced is insufficient to move glucose into cells." (PMID 39810844, 2025). "Increased maternal age potentially exacerbates insulin resistance and beta-cell dysfunctiondue to chronic low-grade inflammation and progressive decline in insulin sensitivity." (PMID 41393417, 2025). "Feeding whole/ground pecan or pecan polyphenol extract with a high fat diet reduced fat mass, serum cholesterol, insulin, and insulin resistance (HOMA-IR) by 44, 40, 74, and 91%, respectively, compared to the high fat fed group." (PMID 41373975, 2025). "This condition results in a decreased efficiency of insulin in glucose uptake and utilization, clinically defined as insulin resistance." (PMID 39966707, 2025). "Insulin resistance elevates circulating insulin and serum glucose levels and enhances inflammation; all these factors can fuel cancer progression." (PMID 40361337, 2025). "PTP1B KO mice had better insulin sensitivity, enhanced muscle and liver IR phosphorylation, and resistance to high-fat diet-induced obesity and insulin resistance." (PMID 40141412, 2025). "In Asian individuals with prediabetes, impaired insulin secretion plays a more important role in glucose dysregulation than in Western individuals, although mild insulin resistance is also present." (PMID 41214697, 2025). "Research involving both lean and obese individuals showed that insulin-induced vasodilation through PI3K signaling is compromised in those with insulin resistance." (PMID 40725728, 2025). "Concurrently, catecholamines exacerbate insulin resistance by promoting lipolysis in adipose tissue and impairing insulin-mediated glucose uptake in skeletal muscle through α1- and β-receptors." (PMID 41585808, 2025). "In adipose tissue insulin resistance (AT-IR), inflammation exerts a dominant disruptive influence on insulin signaling, impairing glucose uptake and lipid storage." (PMID 41153663, 2025). "Insulin resistance itself is characterized by a diminished cellular response to insulin, leading to hyperinsulinemia and a metabolic milieu conducive to tumorigenesis." (PMID 41300804, 2025). "Each procedure enhances insulin sensitivity, reduces insulin resistance, and can decrease blood sugar levels." (PMID 39859139, 2025). "It is a heterogeneous metabolic disease characterized by chronic hyperglycemia due to a combination of insulin resistance and inadequate insulin secretion." (PMID 41373704, 2025). "Hepatitis viruses can induce the expression of suppressor of cytokine signaling (SOCS), a group of proteins that negatively regulate cytokine receptor signaling via the JAK/STAT pathway, thereby disrupting insulin signaling and promoting insulin resistance." (PMID 40918255, 2025). "T2D is the result of the combination of insulin resistance and impaired insulin secretory capacity, and the presence of insulin resistance has been associated with impaired metabolic flexibility, i.e. the capacity to switch between fuel sources." (PMID 40318136, 2025). "Perinatal exposure to PFOS at doses of 0.3 and 3.0 mg/kg·d induced elevated serum insulin levels, increased insulin resistance index, and impaired β-cell function in adult offspring rats." (PMID 41048434, 2025).
Insulin resistance (continued). "The gut microbiota and its metabolites are involved in the regulation of insulin resistance and insulin sensitivity through multiple mechanisms, including inflammatory factors, microbial metabolite-related networks, and the immune response." (PMID 41394123, 2025). "Research shows that insulin resistance, reduced insulin sensitivity, and elevated blood glucose levels can precede the diagnosis of T2DM by up to 13 years." (PMID 40282189, 2025). "Moderate IR expression; endothelial insulin signaling is physiologically important but can be selectively impaired in insulin resistance." (PMID 41301488, 2025). "His requirement for insulin was likely a result of the compounded effects of MODY and insulin resistance (attributable to presence of background polygenic risk factors)." (PMID 39717432, 2025). "Insulin resistance is defined as a reducedresponsiveness of target tissues to elevated insulin levels, characterized byimpaired glucose uptake, decreased glycogen synthesis, and diminished lipidoxidation capacity." (PMID 40475723, 2025). "In parallel, insulin-stimulated glucose uptake was markedly diminished in these cells, further indicating the onset of insulin resistance." (PMID 41515983, 2025). "Due to the inhibition of insulin sensitivity and glucose uptake in hepatocytes, an obesity-induced reduction in miR-141-3p can result in insulin resistance." (PMID 40565979, 2025). "Key components of insulin signalling, such as the insulin receptor and Akt, can be O-GlcNAcylated at the same phosphorylation site, worsening insulin resistance and diminishing the cardioprotective effect." (PMID 40243689, 2025). "A greater number of abnormal OGTT values indicates delayed peak insulin secretion, more severe insulin resistance, and a tendency toward prolonged hyperglycemia in the postpartum period." (PMID 40626241, 2025). "Our findings demonstrate that CDDO-EA protects from obesity-induced insulin resistance by inhibiting weight gain due to reduced food intake and improving insulin sensitivity and glucose metabolism." (PMID 40564946, 2025). "The decrease in insulin resistance despite reduced β-cell function can be explained by a compensatory increase in peripheral insulin sensitivity, as described in the literature following partial pancreatectomy." (PMID 40205383, 2025). "Inflammation in adipose tissue is mediated by the secretion of pro-inflammatory cytokines such as tumor necrosis factor-alpha (TNF-α) and interleukin-6 (IL-6), which can impair insulin signaling and promote insulin resistance." (PMID 40672421, 2025). "Insulin resistance is characterized by impaired insulin uptake or response by insulin-sensitive cells, resulting in elevated insulin production without corresponding decreases in blood glucose levels." (PMID 40144769, 2025). "We also examined the influence of MI-883 on glucose homeostasis, glycemia, insulin levels, and insulin resistance in humanized PXR-CAR-CYP3A4/3A7 mice." (PMID 39915454, 2025). "These cytokines are key mediators of inflammatory responses and are frequently elevated in conditions of insulin resistance, attributable to their impact on impairing insulin signaling pathways, leading to hepatic insulin resistance." (PMID 40149935, 2025). "Studies in mice show that TNF administration induces insulin resistance, while its inhibition improves insulin sensitivity." (PMID 40453076, 2025). "The progression of MASLD/MASH is thought to involve not only systemic insulin resistance and glucose intolerance but also deteriorating insulin resistance within adipose tissue." (PMID 41282540, 2025). "The chronic systemic inflammatory process, particularly elevated TNF-α levels, contributes to the development of insulin resistance by decreasing insulin sensitivity." (PMID 41300682, 2025).
Insulin resistance (continued). "It is also anticipated that the co-conditioning of cells with both insulin resistance and atrophy will lead to a further reduction in insulin sensitivity, mitochondrial function, and BCAA utilization." (PMID 40422898, 2025). "Recent report evident that dysregulation of insulin signalling in GD occurs due to chronic inflammation, contribute in development of insulin resistance." (PMID 40126146, 2025). "Chronic hyperglycemia, high free fatty acidemia, pregnancy, and increased levels of insulin-antagonistic hormones contribute to insulin resistance." (PMID 41567335, 2025). "Inflammatory mediators like TNF-α and IL-1β can impede insulin signaling pathways, intensifying insulin resistance and ultimately contributing to the advancement of T2DM and the onset of associated complications." (PMID 40519559, 2025). "Driven by the decreased insulin levels, delayed inulin supplementation reduced the homoeostatic model assessment of insulin resistance (HOMA-IR) as much as simultaneous inulin supplementation did." (PMID 40954286, 2025). "Higher fasting insulin levels attributed to increased insulin resistance were correlated with lower LPL levels in the peripheral bloodstream among participants classified as NGT." (PMID 40507147, 2025). "These assessments were conducted under basal conditions and following treatment with either tumor necrosis factor alpha (TNF-α) to induce insulin resistance or metformin to promote insulin sensitivity." (PMID 41574186, 2025). "Excess visceral fat can secrete higher levels of hormones such as leptin and resistin, disrupting insulin signaling, aggravating insulin resistance, and impairing cholesterol metabolism and gallbladder function." (PMID 41287115, 2025). "Collectively, these mechanisms contribute to a reduction in insulin sensitivity, resulting in insulin resistance and subsequent hyperinsulinemia." (PMID 41301787, 2025). "T2DM, as a chronic metabolic disorder, is characterized by insulin resistance and impaired insulin secretion, often accompanied by a range of complications that pose significant threats to patient health." (PMID 41426986, 2025). "Insulin resistance (IR) is a condition in which the body’s sensitivity to insulin decreases, leading to ineffective uptake and utilization of blood glucose by target tissues and cells." (PMID 39931234, 2025). "Pathophysiological, GDM and T2DM are similar in that they both have insulin resistance concurrent with impaired insulin actions and malfunction of the pancreatic β-cell." (PMID 39941139, 2025). "Myeloid IKKβ KO mice maintained overall insulin sensitivity and were protected from insulin resistance." (PMID 40764506, 2025). "Insulin resistance is a key pathophysiological feature of type 2 diabetes that occurs when the body’s cells become less sensitive to the effects of insulin and its downstream metabolic actions under normal serum glucose concentration." (PMID 40136728, 2025). "This metabolically active visceral tissue secretes free fatty acids (FFAs) and their metabolites, including acyl-coenzyme A, ceramides, and diacylglycerol, which impair cellular insulin responsiveness, leading to insulin resistance and elevated FBG levels." (PMID 40416377, 2025). "Chronic hyperglycemia, insulin resistance, and ineffective insulin effect and secretion are hallmarks of T2DM, leading to many serious secondary complications." (PMID 39861406, 2025). "It is characterized by insulin resistance, which is the reduced responsiveness of cells to insulin, and a reduction in insulin production by the pancreas." (PMID 40697264, 2025). "Glucose transport is rate-limiting for glucose metabolism in muscle and fat, and the impaired insulin-responsive glucose transport system is the key abnormality of glucose intolerance accompanied by insulin resistance." (PMID 39150031, 2025). "This chronic inflammatory environment alters insulin signaling, thereby exacerbating insulin resistance." (PMID 40864980, 2025).
Insulin resistance (continued). "Adiposity, insulin resistance in skeletal muscle, and decreased insulin production by pancreatic β cells which are responsible for synthesizing and secreting insulin, were the most important principal diabetogenic factors." (PMID 40862129, 2025). "First, HDL-C possesses various potential anti-diabetic properties, such as enhancing insulin secretion, promoting β-cell protection, and alleviating insulin resistance." (PMID 40405966, 2025). "We investigated the relationship between SUA and FPG, insulin levels, and insulin resistance [homeostatic model assessment of insulin resistance (HOMA-IR) ≥2.65]." (PMID 40283451, 2025). "For instance, low n-6 PUFA/n3-PUFA ratio have been shown to decrease insulin levels and improve insulin resistance in humans." (PMID 40387078, 2025). "At the cellular level, insulin resistance develops when cells become less responsive to insulin signaling, primarily through the disruption of the PI3K/AKT pathway." (PMID 40076293, 2025). "Cu accumulation promotes the generation of ROS, which impedes insulin signaling pathways, thereby contributing to the development of insulin resistance." (PMID 41301408, 2025). "Over time, chronic insulin resistance overwhelms β-cells, leading to progressive dysfunction, impaired insulin secretion, and overt hyperglycemia." (PMID 40141237, 2025). "Metabolic improvementsincluded a reduction in insulin levels (from 67.25 ± 47.58 to 39.66 ±21.11 pmol/L, p = 0.033) and insulin resistance (from 2.19 ± 1.57to 1.25 ± 0.69, p = 0.029), while fasting glucose levels remainedstable." (PMID 40630882, 2025). "Metabolic syndrome is a metabolic disorder characterized by obesity, hypertension, disturbed blood lipid profile, glucose intolerance, elevated blood pressure, impaired glucose tolerance, hyperinsulinemia, and impaired insulin action or insulin resistance." (PMID 39859066, 2025). "Although hormonal effects vary and remain incompletely understood, insulin resistance, characterized by reduced insulin effectiveness affecting glucose, lipid, and protein metabolism, constitutes a key mechanism underlying common surgical complications." (PMID 40284879, 2025). "Elevated temperatures trigger inflammatory cytokines like TNF-α and IL-6 in adipose tissue, which disrupt insulin signaling and contribute to insulin resistance." (PMID 41036090, 2025). "During nutrient excess, insulin resistance can impair insulin-mediated nutrient and energy responses, disrupting nerve metabolism, and leading to nerve injury." (PMID 40671105, 2025). "Insulin influences inflammation through NF-κB suppression, with insulin resistance potentially worsening viral pathogenesis." (PMID 40176892, 2025). "Numerous research studies have established the correlation between oxidative stress and the pathophysiology of insulin resistance through the suppression of insulin signaling and dysregulation of adipocytokines." (PMID 40509282, 2025). "PPARγ activators protect islet beta cells from fatty acid-induced damage, promote insulin secretion, and reduce insulin resistance." (PMID 40650120, 2025). "HPA axis dysfunction raises blood cortisol levels, which increases glucose and insulin levels, leading to insulin resistance, dyslipidemia, high blood pressure and obesity." (PMID 40292556, 2025). "Another study observed that, within days after RYGB, there were increased postprandial levels of GLP-1, OXM, and insulin sensitivity, alongside a decrease in fasting glucose, reduced insulin resistance, and improved satiety." (PMID 41155711, 2025). "Fasting hyperglycemia indicates primarily hepatic insulin resistance (impaired insulin sensitivity), while post-load hyperglycemia indicates defective insulin secretion and insulin resistance at the skeletal muscle level." (PMID 40569563, 2025).
Insulin resistance (continued). "SIRT1 has been strongly associated not only with neuroprotection but also with the amelioration of insulin resistance by silencing the expression of the protein tyrosine phosphatase 1B, a major negative regulator of insulin action." (PMID 40137124, 2025). "Brain insulin resistance results from impaired insulin signaling, mainly through the insulin receptor substrate 1 (IRS-1)/phosphatidylinositol 3-kinase (PI3K)/protein kinase B (Akt) pathway." (PMID 40362446, 2025). "In overweight or obese individuals, Type 2 diabetes is most likely to result from adiposity‐induced insulin resistance, followed by compensatory insulin secretion and subsequent β‐cell dysfunction, and ultimately manifest with overt hyperglycemia." (PMID 40171822, 2025). "Mitochondrial dysfunction leads to increased release of ROS and lipid metabolites and decreased β-oxidation and ATP production, affecting insulin secretion, signaling and function, further exacerbating insulin resistance." (PMID 40671123, 2025). "Factors which are involved in the onset and progression of hyperglycemia are, for example, dysfunction of the islets of Langerhans, decreased secretion of insulin, impaired glucose utilization, and insulin resistance." (PMID 39859258, 2025). "The treatment of patients with type 2 diabetes involves biochemotherapies, employing insulin secretion promoters, the suppression of glucose absorption, and reduction of insulin resistance." (PMID 40286074, 2025). "The pathogenesis of impaired glucose homeostasis is characterized by insulin resistance and reduced insulin secretion, and the dominant factors can differ between races and individuals." (PMID 41214697, 2025). "Tinospora cordifolia enhances pancreatic β-cell function and endogenous insulin secretion while reducing insulin resistance." (PMID 40083990, 2025). "These vesicles, enriched with specific microRNAs, regulate glucose homeostasis, insulin sensitivity, and lipid metabolism, contributing to the onset and progression of insulin resistance, hepatic steatosis, and systemic metabolic dysfunction." (PMID 40001534, 2025). "MAPK-related signaling pathways are also involved in modulating insulin signaling, while the activation of these pathways can also impair insulin sensitivity, leading to insulin resistance in skeletal muscle and adipose tissue." (PMID 41150789, 2025). "In a state of insulin resistance, insulin signaling pathways are impaired, including reduced phosphorylation of insulin receptors and their downstream signaling molecules, such as Akt proteins." (PMID 40235664, 2025). "The disease begins with insulin resistance in key tissues such as the liver, muscle, and adipose tissue, followed by progressive β-cell dysfunction leading to reduced insulin secretion." (PMID 40565043, 2025). "Activity VitB6 rescues DNA damage treating impaired PI3K, so it can enhance insulin sensitivity and attenuating insulin resistance, and VitB6 has been proved that VitB6 can induced autophagy inhibiting the apoptosis of β‐cells via the mTOR‐dependent pathway." (PMID 40625625, 2025). "In mice with diet‐induced obesity and insulin resistance, partial loss of DRP1 was sufficient to enhance skeletal muscle insulin sensitivity [Reference S2]." (PMID 40035128, 2025). "Collectively, ERRα integrates metabolic signals to regulate glucose output, uptake, and insulin action, positioning it as a promising therapeutic target for insulin resistance, T2DM, and metabolic syndrome." (PMID 40926269, 2025). "Tumor necrosis factor α (TNFα), a potent inflammatory cytokine, promotes insulin resistance through the downregulation of key genes required for normal insulin function." (PMID 41012578, 2025). "Patient #4 was overweight and had insulin resistance (HOMA-IR: 10.7) with a positive family history; his mother carried the same variant and had a history of gestational diabetes requiring insulin therapy." (PMID 41153735, 2025).